MAMLD1 (mastermind like domain containing 1)
Description:
Transactivates the HES3 promoter independently of NOTCH proteins. HES3 is a non-canonical NOTCH target gene which lacks binding sites for RBPJ.
Synonyms: CG1; CXorf6; F18; HYSP2
Tractability: No criterion of Open Targets' tractability assessment is met for any kind of drug.
Gene: Protein-coding gene on chromosome X (150,361,422 to 150,514,178, forward strand). Ensembl gene ENSG00000013619.
Subcellular location: Nucleus
Subcellular location (Human Protein Atlas): Nucleoplasm; Centrosome; Golgi apparatus; Nuclear bodies
Pathways (Reactome):
Signal Transduction: NOTCH1 Intracellular Domain Regulates Transcription; NOTCH2 intracellular domain regulates transcription; NOTCH3 Intracellular Domain Regulates Transcription; NOTCH4 Intracellular Domain Regulates Transcription; Pre-NOTCH Transcription and Translation
Developmental Biology: Differentiation of naive CD4+ T cells to T helper 2 cells (Th2 cells); Formation of paraxial mesoderm; Regulation of gene expression in late stage (branching morphogenesis) pancreatic bud precursor cells
Disease: Constitutive Signaling by NOTCH1 HD+PEST Domain Mutants; Constitutive Signaling by NOTCH1 PEST Domain Mutants
Gene expression (Transcription): Notch-HLH transcription pathway; RUNX3 regulates NOTCH signaling
Gene Ontology:
Biological process: male gonad development; regulation of transcription by RNA polymerase II
Cellular component: nuclear body; nucleoplasm; nucleus
Homologues: Orthologues: chimpanzee MAMLD1 (89% identical), macaque MAMLD1 (88% identical), pig MAMLD1 (76% identical), guinea pig MAMLD1 (75% identical), mouse Mamld1 (71% identical), dog MAMLD1 (66% identical), tropical clawed frog mamld1 (37% identical).